CRYL1 (crystallin lambda 1)
Description:
Catalyzes the conversion of L-gulonate to 3-dehydro-L-gulonate. It also exhibits low dehydrogenase activity toward L-3-hydroxybutyrate (HBA) and L-threonate. Utilizes NAD as the sole cosubstrate and shows no activity with NADP.
Synonyms: Gul3DH; GDH; lambda-CRY; MGC149525; MGC149526; HEL30
Tractability: Small molecule: a structure with a bound ligand is known; it has a high-quality binding pocket. Antibody: the Human Protein Atlas places it where antibodies can reach. PROTAC: ubiquitination databases record sites on it; its protein half-life has been measured.
Gene: Protein-coding gene on chromosome 13 (20,403,666 to 20,525,873, reverse strand). Ensembl gene ENSG00000165475.
Subcellular location: Cytoplasm
Subcellular location (Human Protein Atlas): Nucleoli; Nucleoplasm; Golgi apparatus; Plasma membrane
Pathways (Reactome):
Metabolism: Formation of xylulose-5-phosphate
Gene Ontology:
Molecular function: L-gulonate 3-dehydrogenase activity; NAD+ binding; protein homodimerization activity; oxidoreductase activity; oxidoreductase activity, acting on the CH-OH group of donors, NAD or NADP as acceptor
Biological process: fatty acid metabolic process
Cellular component: extracellular exosome; cytoplasm; cytosol
Genetic constraint (gnomAD): Loss-of-function variants: 28 observed, 29.59 expected, observed/expected ratio (o/e) 0.95, 90% interval 0.7 to 1.3. The upper end of that interval is the gene's LOEUF score, 1.3, which puts it in group 5 of 6, group 1 being the genes least tolerant of losing a copy. Missense variants: 360 observed, 364.93 expected, observed/expected ratio (o/e) 0.99, 90% interval 0.9 to 1.08. Synonymous variants: 138 observed, 142.67 expected, observed/expected ratio (o/e) 0.97, 90% interval 0.84 to 1.11.
Homologues: Orthologues: chimpanzee CRYL1 (100% identical), guinea pig CRYL1 (85% identical), mouse Cryl1 (84% identical), rabbit CRYL1 (83% identical), dog CRYL1 (82% identical), rat Cryl1 (82% identical), macaque CRYL1 (80% identical), pig CRYL1 (76% identical), tropical clawed frog cryl1 (62% identical), zebrafish cryl1 (54% identical), Drosophila melanogaster Had1 (50% identical), Drosophila melanogaster Had2 (45% identical), and 1 more. Paralogues in human: EHHADH (23% identical), HADH (22% identical), HADHA (22% identical).
Diseases named in the same sentence as CRYL1 in open-access papers:
CRYL1 is named in the same sentence as 20 diseases in open-access papers, as found by Europe PMC text mining. Sharing a sentence is not in itself a finding about the gene and the disease. The quoted sentences say what the papers report.
hepatocellular carcinoma (4 papers, 2017 to 2023). A malignant tumor that arises from hepatocytes. "More recently, bioinformatics analysis has shown that CRYL1 is a shared susceptibility gene between late-stage hepatocellular carcinoma and high HBA1c, and that the amount of CRYL1 is inversely related to tumor stage." (PMID 36607984, 2023). "There are similarities between obesogenic and oncogenic states, namely cellular proliferation and inflammation, and it is interesting to note, that in this study two of the genes with significant methylation, DLC1 and CRYL1, are associated with hepatocellular carcinoma." (PMID 28068899, 2017). "CRYL1 is a well-known tumor suppressor in hepatocellular carcinoma, and is related to the uronate cycle functions as an alternative glucose metabolic pathway." (PMID 33324981, 2021).
hearing loss (3 papers, 2023 to 2025). "Unsolved cases after the first step would be analyzed by a comprehensive NGS panel able to detect all relevant CRYL1 deletions, to maximize diagnostic yield of hearing loss in clinical settings." (PMID 40565562, 2025). "In this work, we identified a novel 200 kb deletion spanning more than 20 kb each side of the CRYL1 locus and present in heterozygosis in three unrelated hearing loss patients from northwestern Spain who are also heterozygous for the most prevalent pathogenic GJB2 mutation in Europeans (c.35delG)." (PMID 40565562, 2025). "GS of the remaining 15 cases yielded diagnoses in three individuals, including the identification of deletions in LOXHD1 and STRC, and a recently characterized 125 kb deletion overlapping CRYL1, which refines a critical upstream regulatory region associated with GJB2-related hearing loss." (PMID 41367487, 2025). "However, together with GJB2 and GJB6 (which are outside of the microdeletion interval), CRYL1 constitutes part of the DFNB1 locus, which accounts for nearly half of the sensorineural hearing loss in certain populations." (PMID 37239394, 2023). "This novel CRYL1 deletion has not been detected in individuals from gnomADv4.1.0, nor in 2052 alleles from a control local population, and its presence in compound heterozygosity with c.35delG segregates with hearing loss." (PMID 40565562, 2025). "In support of this, there are several hearing-loss-associated DFNB1 microdeletions reported in the literature and in DECIPHER that include CRYL1 but neither of the connexins." (PMID 37239394, 2023).
Alzheimer disease (2 papers, 2017 to 2023). A progressive, neurodegenerative disease characterized by loss of function and death of nerve cells in several areas of the brain leading to loss of cognitive function such as memory and language. "APOE, HP, and CRYL1 have all been associated with Alzheimer’s Disease, the pathology of which involves lipid and cholesterol pathways." (PMID 28206976, 2017). "The variant rs7989332 in CRYL1 was found to interact with rs6455128 in KHDRBS2 (KH domain containing, RNA binding, signal transduction associated 2) and be protective against Alzheimer’s Disease." (PMID 36607984, 2023).
deafness (1 paper, 2025). An inherited or acquired condition characterized by the complete loss of the ability to hear from one or both ears. "In our opinion, all genetic diagnostic strategies for hereditary deafness that claim to be comprehensive should be able to detect any copy number alteration affecting the 62 kb CRYL1 MCR." (PMID 40565562, 2025).
glioma (1 paper, 2021). A benign or malignant brain and spinal cord tumor that arises from glial cells (astrocytes, oligodendrocytes, ependymal cells). "The present study was novel in building a uronic acid metabolic process–related signature involving five genes (UGT8, DCXR, SORD, XYLB, and CRYL1) to predict the survival of glioma in the CGGA database." (PMID 33324981, 2021).
intrauterine growth restriction (1 paper, 2025). "CRYL1 is associated with sexual behavior in Rasa Aragonesa rams and is a useful diagnostic target for intrauterine growth restriction in sheep." (PMID 40149467, 2025).
tumor (7 papers, 2017 to 2024). "PTGR1, C1orf115, CRYL1, ALDOB, and SULT1B1 may be tumor suppressor genes involved in GC progression." (PMID 38737262, 2024). "In addition, these CENPF-related genes exhibited the expression differences between normal and tumor tissues: the expression of TOP2A or KIF23 was significantly upregulated in LPS, while that of BAG1,PNPLA2, CRYL1 or GRN was significantly downregulated in LPS or MRCLPS compared to normal tissues." (PMID 37108172, 2023).
cancer (4 papers, 2012 to 2024). A tumor composed of atypical neoplastic, often pleomorphic cells that invade other tissues. "Furthermore, little is known about the roles of ALDOB, CRYL1, and C1orf115 in human cancer, especially GC, so future studies on these genes are needed." (PMID 38737262, 2024).
CRYL1 also shares sentences with these, for which no sentence is quoted: brain disorder (1 paper); breast carcinoma (1); cholestasis (1); diabetes (1); glaucoma (1); glioblastoma (1); liposarcoma (1); oral cancer (1); osteosarcoma (1); pulmonary hypertension (1); sickle cell disease (1); uveitis (1).